MIR1282 (microRNA 1282)
Synonyms: hsa-mir-1282; MIRN1282
Gene: MicroRNA gene on chromosome 15 (43,793,659 to 43,793,759, reverse strand). Ensembl gene ENSG00000221792.
Homologues: Orthologues: chimpanzee ptr-mir-1282-1 (100% identical), macaque MIR1282 (100% identical), mouse Gm22953 (100% identical), pig MIR1282 (100% identical), rabbit MIR1282 (100% identical).